CD36 (CD36 molecule (CD36 blood group))
Diseases named in the same sentence as CD36 in open-access papers (continued):
Sharing a sentence is not in itself a finding about the gene and the disease.
atherosclerosis (continued). "Consequently, antcin K decreased CD36 expression and increased KLF4 expression, which enhanced oxidized LDL efflux in macrophages, alleviated lipid deposition, and decreased atherosclerotic lesions, thereby reducing atherosclerosis formation." (PMID 36365265, 2022). "As a fatty acid transporter, CD36 mediates lipid deposition, and also participates in the inflammatory response and mitochondrial FAO, which contributes to the regulation of chronic metabolic diseases, including atherosclerosis and non-alcoholic steatohepatitis." (PMID 34021126, 2021). "However, since CD36 and LOX-1 are molecules in atherosclerosis development and progression, their pharmacological inhibition would be an exciting and promising avenue in developing therapeutic agents to alleviate or even reverse the atherosclerotic plaque formation." (PMID 33440673, 2021). "However, there is no direct evidence that specific knockout of CD36 or LOX-1 on platelets in atherosclerosis-prone mice affects atherosclerotic plaque formation." (PMID 33371312, 2020). "Moreover, the fatty acid transporter sCD36 has been considered a potential biomarker of atherosclerosis given that in animal models of atherosclerosis, absence of CD36 has been reported to result in a reduction of atherosclerosis." (PMID 32498389, 2020). "CD36 is involved in non-classical monocyte patrolling during atherosclerosis induction." (PMID 39649554, 2020). "When crossed with apoE-negative mice, CD36 null mice were resistant to developing atherosclerosis." (PMID 29883404, 2018). "Similarly, ApoE-null mice lacking CD36 and SR-A were not protected against atherosclerosis development but observed a reduction in the expression of pro-inflammatory cytokines and macrophage apoptosis." (PMID 29113088, 2017). "The mechanism of QSYQ inhibiting atherosclerosis included promoting Treg immigration into atherosclerotic plaque, inhibiting the secretion of IL17 by Th17 in spleen and plaque, blocking oxidized LDL phagocytized by macrophage through CD36, and increasing the expression of LXR-α and ABCG5 in liver." (PMID 29137256, 2017). "Previous studies have illustrated that CAV-1 may be involved at the earlies stages of atherosclerosis development through increased LDL particle transcytosis, endothelial cells activation, and induced protherogenic molecule CD36 and vascular cell adhesion molecule-1 expression." (PMID 27124120, 2016). "Together, these results show a role for CD36/SR-B2 at multiple points in Pg mediated enhanced atherosclerosis, and support the hypothesis that TLR-CD36/SR-B2 mediated IL1β generation, leading to increased foam cell formation, may be essential to the enhancement in atherosclerosis lesion observed." (PMID 25938460, 2015). "Thus, downregulation of CD36 and upregulation of ABCA1 in macrophages may have contributed to the slower progression of atherosclerosis in the brachiocephalic artery of AdipoR2-/-ApoE-/- mice in the present study." (PMID 24324556, 2013). "The protective effect of CD36-deficiency was shown to be macrophage-dependent, since mice lacking CD36 selectively in macrophages were protected against atherosclerosis, whilst re-introduction of CD36 expressing macrophages resulted in an increased lesion area." (PMID 24324556, 2013). "The CD36 is a glycoprotein located in membrane and plays various cellular processes such as lipid transport, immune regulation, coagulation and atherosclerosis, and the CD36 structure is related to scavenger receptor B1, and highly binds to oxidized LDL, which induced atherosclerosis process." (PMID 23249574, 2012). "A previous study demonstrated that the absence of CD36 on macrophages may protect against atherosclerosis in ApoE-/- mice, strongly supporting a pro-atherogenic role for CD36." (PMID 21486455, 2011).
atherosclerosis (continued). "As TGF-β downregulates scavenger receptors, such as scavenger receptor type A (SR-A) I/II and CD36, and upregulates ATP-binding cassette (ABC) transporters, ABCA1 and ABCG1, TGF-β is also thought to have protective effects against the development of atherosclerosis." (PMID 21199582, 2011). "Fatty acid translocase (FAT or CD36) is a cell-surface glycoprotein that functions as a multiligand receptor/transporter involved in various diverse physiological processes and disorders, including atherosclerosis, dyslipidemia, insulin resistance and diabetes." (PMID 17640331, 2007). "Additionally, CD36-targeted LNs exhibited improved EGCG stability and targeted delivery, with reduced liver accumulation relative to native EGCG, positioning it as a promising strategy for macrophage-targeted therapy in atherosclerosis and other macrophage-driven inflammatory conditions." (PMID 40871008, 2025). "Moreover, ssGSEA analysis of model genes in the marker gene set of the GSEA database revealed that CD36 and S100A10's activities in the respective marker gene sets were precisely opposite to CSNK1A1, highlighting distinct regulatory roles of these genes in the context of atherosclerosis." (PMID 39660117, 2024). "Therefore, CD36 can function in a wide range of processes not always related to FA uptake, including apoptosis, angiogenesis, phagocytosis, thrombosis, inflammation, and atherosclerosis." (PMID 29883404, 2018). "The absence of modifications in CD11c, CD11b, and CD36 levels in IR and SCA groups suggest a very early stage in the development of atherosclerosis in these asymptomatic individuals." (PMID 35958411, 2022). "Compared with CD36, LOX‐1 is able to bind moderately modified, but not fully oxidized LDL suggesting for crucial role of this receptor in initial stages of atherosclerosis." (PMID 26493158, 2016).
Obesity (292 papers, 2009 to 2026). Accumulation of substantial excess body fat. "Numerous studies have established CD36 gene as a candidate gene associated with traits such as obesity (OB), fat profile, fat deposition, body weight (BW), carcass characteristics, disease resistance and health indices in mammals." (PMID 40087777, 2025). "CD36 serves as a marker for human adipocyte progenitors and mononuclear phagocytes, and its expression is upregulated during obesity and associated with increased adipogenesis." (PMID 40395977, 2025). "Macrophage uptake of lipids through the scavenger receptor CD36 is associated with altered macrophage functions and disease pathogenesis in obesity and atherosclerosis." (PMID 40717126, 2025). "Wistar rats were chosen in this study for their higher susceptibility to HFD-induced obesity than Sprague-Dawley rats, attributed to elevated cluster of differentiation 36 (CD36) and lipoprotein lipase expression." (PMID 40563378, 2025). "CD36 has been implicated in maintaining lymphatic vessel integrity, which is associated with obesity and type 2 diabetes models." (PMID 40713754, 2025). "Upregulation of CD36, a key FAs transporter, and subsequent FAs overloading have been strongly correlated with AF and its risk factors, such as obesity, diabetes, and aging." (PMID 40943496, 2025). "High levels of CD36 are linked to increased inflammation and impaired insulin signaling in conditions like obesity and type 2 diabetes." (PMID 41465460, 2025). "As Kir2.1 is well known to be inhibited by fatty acid derivatives and obesity is strongly associated with elevated circulating fatty acids, we next tested the role of the fatty acid translocase CD36 in mediating VAT-induced Kir2.1 dysfunction." (PMID 38586877, 2024). "Endospanin 1 controls surface abundance of lipid translocase CD36 in adipocytes, which allows dissociation of obesity from diabetes, and its reduction is linked to metabolically healthy obesity." (PMID 38716728, 2024). "We further reveal a role for CD36 as a major contributor to VAT-mediated Kir2.1 and endothelial dysfunction, suggesting that CD36 offers a potential target for preventing the early development of obesity-associated cardiovascular disease." (PMID 38586877, 2024). "CD36 has been shown to be a key player in lipid metabolism and recently in obesity- associated inflammation and IR29–37." (PMID 37980376, 2023). "Blood FAs are associated with obesity and are associated with chronic inflammation through increased CD36, TLR4, and NF-κB p65 in monocytes." (PMID 37403139, 2023). "Collectively, these data show that blocking TSP1/CD36 interaction by CD36 peptide alleviates obesity-associated kidney inflammation and improves kidney function." (PMID 37980376, 2023). "CD36 deficiency protects against diet‐induced obesity, intramuscular lipid deposition, and oxidative stress." (PMID 40625574, 2023). "The mechanisms by which CD36 peptide treatment improved obesity-associated glucose homeostasis was determined." (PMID 37980376, 2023). "In summary, our studies demonstrated that CD36 peptide treatment reduced obesity associated chronic inflammation, leading to improved glucose homeostasis and reduced kidney and liver damage in obese mice." (PMID 37980376, 2023). "Obesity associated hypertriglyceridemia and hypercholesterolemia were also reduced by CD36 peptide treatment." (PMID 37980376, 2023). "CD36 has also been linked to metabolic diseases such as insulin resistance, obesity and type 2 diabetes mellitus, with an increasing subpopulation of overweight individuals in Western societies." (PMID 37004042, 2023). "In this study, the therapeutic potential of TSP1 antagonist peptide (CD36 peptide) in obesity-associated chronic inflammation and metabolic dysfunction was tested in HF diet-induced obese mouse model." (PMID 37980376, 2023). "In the present study, we determined the effects of common CD36 variants and CD36 gene methylation on obesity and its related complication type 2 diabetes." (PMID 35982478, 2022).
Obesity (continued). "The regulatory circuit of the CD36 gene that determines muscle cell proliferation should be further clarified and can be used for developing new therapeutics to treat obesity-associated muscle wasting." (PMID 36111143, 2022). "CD36 is a fatty translocase acid protein that facilitates fatty acid uptake in various cell types, which is closely associated with obesity." (PMID 36465448, 2022). "We discovered for the first time a BCL6/CD36 axis that centrally modulates obesity-associated NAFLD." (PMID 35436984, 2022). "CD36 alterations have been implicated in numerous disorders, such as obesity and inflammatory conditions." (PMID 36310155, 2022). "According to Bokor and al., the rs1527483 of the CD36 gene has been associated with the onset of obesity by increasing the percentage of body fat and, consequently, the BMI." (PMID 35982478, 2022). "Our study showed that the AA/AC genotype of a promoter polymorphism of CD36 rs3211867 increases exposure to obesity and hypercholesterolemia." (PMID 35982478, 2022). "Lipid accumulation in obesity and diabetes is also associated with increased CD36 expression in skeletal muscle." (PMID 36467688, 2022). "Genetic variation at the CD36 loci has been associated with obesity and lipid components of the metabolic syndrome." (PMID 36465448, 2022). "Obesity was associated with greater protein expression of CD36/SR-B2 in the adipocytes originated from ADMSCs of both depots and FATP4 (only in ADMSCs derived from subcutaneous depots)." (PMID 35563741, 2022). "Partial or total CD36 deficiency is associated with abnormal blood lipid profile and with vascular stiffening, which are predictors of obesity/diabetes-associated cardiovascular events." (PMID 36061565, 2022). "Low-function or low-expression polymorphisms of CD36 were associated with obesity owing to a reduced lipid uptake by scavenger cells and a loss of the oro-sensory perception of fatty nutrients, i.e., fat taste." (PMID 34836380, 2021). "CD36 deficiency alleviates diabetic cardiomyopathy and atherosclerosis and protects against diet-induced obesity, intramuscular lipid deposition, and oxidative stress." (PMID 34827565, 2021). "For example, higher sCD36, a non-cell-bound CD36 found in human plasma that indirectly reflects CD36 expression in tissues, has been linked to obesity, insulin resistance, and diabetes according to recent community-based cohort research." (PMID 34360006, 2021). "Deficiency of CD36 reduces the visceral fat accumulation and thus decreases the progression of obesity." (PMID 34679777, 2021). "It was observed that a high-fat diet or obesity resulted in a loss of CD36 expression in taste bud cells, and its expression was low in models of obesity such as ghrelin-deficient mice." (PMID 34836380, 2021). "Based on these studies, it would be relevant to study the role of CD36 and/or cathepsins in B cell function associated with obesity." (PMID 34957117, 2021). "The elafin-dependent mesenteric fat and hepatic CD36 expression are associated with obesity and liver steatosis in mice." (PMID 32733043, 2020). "CD36 possesses a key role in the alterations of lipid metabolism upon fatty acid oversupply, thus it has been implicated in the etiology of obesity-induced or high fat diet-induced ectopic lipid accumulation and insulin resistance." (PMID 31938068, 2020). "CD36 is associated with obesity and diabetes, and CD36-mediated hepatic fat uptake accelerates the progression of NAFLD." (PMID 33209195, 2020). "In rodent models, it was confirmed that CD36 underlies the progression of obesity-associated metabolic dysfunctions, such as visceral fat accumulation with impairment in glucose clearance and abnormal fasting blood glucose level." (PMID 32796572, 2020). "The presented studies indicate that obesity increases CD36 expression in adipose tissue, which is associated with the stimulation of lipolysis and the development of insulin resistance." (PMID 32796572, 2020).
Obesity (continued). "DNA methylation of CD36 has been studied mostly in relation to lipid metabolism and obesity, whereas changes in CD36 histone marks have been linked to inflammation." (PMID 31379931, 2019). "Genetic mutations in CD36, and changes in protein expression have been repeatedly reported in relation to cardiac artery disease, metabolic syndrome and obesity, malaria, and tumor spreading." (PMID 31379931, 2019). "For example, increased expression of CD36 in adipocytes and adipose tissue macrophages is associated with obesity and inflammation." (PMID 31035848, 2019). "Recently, various studies have revealed results about the relationship between CD36 gene polymorphisms and obesity on the one hand and CD36 gene polymorphisms, hypertension, and CVDs on the other." (PMID 31185924, 2019). "CD36 is a scavenger receptor that has been associated with cellular uptake of lipids in a whole range of cells, and its expression is increased in obesity, MetSy, and diabetes." (PMID 30386406, 2018). "The polymorphisms of CD36 gene, rs1761667, rs1527483, and rs3840546, have been associated with taste perception to and preference for fat (rs1761667, rs1527483), and obesity (rs3840546)." (PMID 29270130, 2017). "The objective of the present study was to examine the impact of CD36 deficiency on obesity-associated oxidative stress and lipotoxicity in heart." (PMID 27195707, 2016). "In this study we demonstrate for the first time that diet-induced obesity, hypertriglyceridemia and hyperinsulinemia associate with defective down-regulation of CD36 by dietary lipid." (PMID 26727015, 2016). "An investigation done in Europe showed a promising result on how CD36 influence individual susceptibility to obesity." (PMID 27127449, 2016). "Previously, we demonstrated that interaction of TSP1 and CD36 contributes to obesity-associated podocytopathy." (PMID 27196103, 2016). "Diet-induced obesity caused an elevation of hepatic Cd36 expression, and this elevation was correlated with the increase in liver TG storage." (PMID 27266874, 2016). "The aim of this study was to determine the impact of CD36 deficiency on cardiac steatosis, oxidative stress and lipotoxicity associated with obesity." (PMID 27195707, 2016). "CD36 deficiency prevented obesity-associated cardiac steatosis and insulin resistance, and reduced NADPH oxidase-dependent ROS production." (PMID 27195707, 2016). "Obesity modestly but significantly enlarged LV end-diastolic diameter (LVEDd) but was corrected by CD36 deficiency." (PMID 26036798, 2015). "Low fatty acid oro-sensory detection in obesity has been attributed to low expression of CD36 protein in the mouse or to AA genotype of rs1761667 polymorphism of CD36 in human beings." (PMID 26556365, 2015). "Similar findings were observed by several other rodent studies and have recently been confirmed in liver biopsies of patients with NAFLD, highlighting the clinical relevance of CD36 in human liver diseases associated with obesity and type 2 diabetes." (PMID 24751397, 2014). "Conversely, HF-feeding and obesity is associated with decreases in lingual CD36 expression, although changes in lingual CD36 protein levels in obese mice has not been confirmed." (PMID 22768116, 2012). "SNPs within CD36, other than the one we found in this study, were linked to obesity in a case-control study." (PMID 23236364, 2012). "Moreover, CYP1B1 deficiency attenuated HFD‐induced obesity and improved glucose tolerance due to the reduced expression of different adipogenic genes such as PPARγ, CD36, FAS, and SCD‐1 and increased expression of genes involved in lipolysis." (PMID 39806854, 2025). "Finally, we list evidence showing how CD36 genetics are related to the predisposition to develop and manage obesity." (PMID 41344388, 2025). "In addition, lingual CD36 is involved in the taste of fat, eating behavior, and obesity risk in rodents and humans." (PMID 40316903, 2025).